REN (renin)
Diseases named in the same sentence as REN in open-access papers (continued):
Sharing a sentence is not in itself a finding about the gene and the disease.
septic shock (3 papers, 2019 to 2022). Shock caused by infection; frequently caused by gram negative bacteria, although some cases have been caused by other bacteria, viruses, fungi, and protozoa; characterized by fever, chills, tachycardia, tachypnea, and hypotension. "Some patients with septic shock are on chronic renin-angiotensin-aldosterone system inhibitor but it is unknown whether the hemodynamic response to AVP differs between patients who are on vs. not on chronic renin-angiotensin-aldosterone system inhibitor(s)." (PMID 30736368, 2019). "Presence of GI bleeding, hemorrhagic shock or septic shock aggravates the shortage of effective arterial blood volume, further activating the sympathetic nervous system, renin–angiotensin–aldosterone system, and non-osmotic release of antidiuretic hormone." (PMID 35545763, 2022).
steatosis (3 papers, 2018 to 2019). Increased lipid within the cytoplasm of cells. "Corroborating with the literature, the dose used in the present study was also observed to decrease blood pressure, and renin–angiotensin II level in mice and attenuated steatosis and inflammation in mice." (PMID 31333451, 2019). "The deregulation of the renin-angiotensin system could explain part of the relation between steatosis and any possible CDV disease." (PMID 30279702, 2018).
stress-induced cardiomyopathy (3 papers, 2020 to 2024). "We found that only inhibitors of the renin-angiotensin system were associated with lower mortality in patients with takotsubo syndrome which is consistent with previous data from the Intertak registry." (PMID 38774915, 2024). "Despite “normalization” of the left ventricular ejection fraction, there is long‐term maladaptive activation of renin‐angiotensin system in patients with takotsubo cardiomyopathy." (PMID 35861811, 2022). "Patients with takotsubo cardiomyopathy had higher renin compared with controls (P=0.03), and out of the 3 takotsubo cardiomyopathy groups, the renin level in the acute group was significantly elevated compared with healthy controls (P=0.03)." (PMID 35861811, 2022). "Here, we investigate if the sequential acute to long‐term response of the renin‐angiotensin and endothelin‐1 systems follows the “normalization” of the left ventricular ejection fraction in patients with takotsubo cardiomyopathy." (PMID 35861811, 2022). "Serum renin concentrations remain persistently elevated after a episode of takotsubo cardiomyopathy (P=0.03 versus controls)." (PMID 35861811, 2022). "We investigate if renin‐angiotensin and endothelin‐1 response pathways follow the same pattern of recovery as left ventricular ejection fraction in patients with takotsubo cardiomyopathy." (PMID 35861811, 2022). "Overall, our findings show that despite “normalization” of the left ventricular ejection fraction, there is long‐term maladaptive activation of renin‐angiotensin system and dysregulation of endothelin‐1 in patients with takotsubo cardiomyopathy." (PMID 35861811, 2022).
systemic inflammatory response syndrome (3 papers, 2014 to 2023). SIRS is a serious condition related to systemic inflammation, organ dysfunction, and organ failure. "Additionally, the downregulation of the ACE2 by the SARS-CoV-2 infection may lead to the increased activation of the renin-angiotensin system (RAS), which may cause systemic vasoconstriction and systemic inflammatory response syndrome (SIRS)." (PMID 36016396, 2022).
Thyroid (3 papers, 2018 to 2021). "It is well known that thyroid diseases can affect cardiac output, peripheral vascular resistance, renal hemodynamics, sodium homeostasis, vascular endothelial function, renin-angiotensin-aldosterone system and many other aspects." (PMID 31174521, 2019). "Thyroid disorders affect the hypothalamic-pituitary-adrenal axis with important consequences on the cardiovascular function in which the renin-angiotensin system plays a major role." (PMID 30555423, 2018).
tubulointerstitial nephritis (3 papers, 2013 to 2024). "Notably, a similar phenotype is often observed in patients with heterozygous variants of UMOD, MUC1, and REN genes, which cause an autosomal dominant form of tubulointerstitial nephritis." (PMID 38674137, 2024). "Uric acid may directly stimulate the renin-angiotensin system and cause renal afferent arteriolopathy and tubulointerstitial nephritis, leading to higher blood pressure." (PMID 24308550, 2013).
acromegaly (2 papers, 2018 to 2021). Acromegaly is an acquired disorder related to excessive production of growth hormone (GH) and characterized by progressive somatic disfigurement (mainly involving the face and extremities) and systemic manifestations. "The retention of water and sodium in acromegaly is realized by GH activating the renin-angiotensin-aldosterone system and thereby promoting atrial natriuretic factor, prostaglandins, and nitric oxide production." (PMID 29531529, 2018).
acute pancreatitis (2 papers, 2006 to 2017). An acute inflammatory process that leads to necrosis of the pancreatic parenchyma. "Recent studies suggest a crucial role for pancreatic renin-angiotensin system during chronic hypoxia in acute pancreatitis and for angiotensin converting enzyme (ACE) inhibitors in reducing pancreatic fibrosis in experimental models." (PMID 17163998, 2006).
acute pyelonephritis (2 papers, 2018 to 2022). "We investigated whether antinatriuretic phenomena [decreases in urinary sodium (uNa) and fractional excretion of sodium (FENa)] seen in children with acute pyelonephritis (APN) are associated with the renin–angiotensin–aldosterone system (RAAS)." (PMID 30200111, 2018).
Allergy (2 papers, 2012 to 2022). An allergy is an immune response or reaction to substances that are usually not harmful. "Vitamin D has effects on renin levels and several publication suggest a link to allergy, anaphylaxis, and Epi-Pen prescription." (PMID 23316249, 2012).
aortic atherosclerosis (2 papers, 2013 to 2025). A atherosclerosis that involves the aorta. "In conclusion, our study suggests progression of aortic atherosclerosis with renin inhibition in patients with established cardiovascular disease, most of whom were receiving evidence-based therapy, with >50% receiving concomitant ACEI/ARB therapy." (PMID 23686372, 2013).
aortic valve calcification (2 papers, 2021 to 2023). "Indeed, multiple clinical trials informed us that lipid-lowering therapy or renin–angiotensin system inhibition did not reduce aortic valve calcification or improve clinical outcomes." (PMID 37754815, 2023).
autism (2 papers, 2016 to 2019). Persistent deficits in social interaction and communication and interaction as well as a markedly restricted repertoire of activity and interest as well as repetitive patterns of behavior. "The results of FoPA on autism-related genes highlight the role of “Renin-angiotensin system” pathway." (PMID 30808299, 2019). "The importance of renin-angiotensin system (RAS) elements in cognition and behavior besides the interaction of angiotensin II (Ang II), the main product of angiotensin-converting enzyme (ACE), with neurotransmitters in CNS, especially dopamine, proposes the involvement of RAS in autism." (PMID 27082637, 2016).
autonomic neuropathy (2 papers, 2017 to 2022). An inherited or acquired peripheral neuropathy affecting the autonomic nervous system. "Factors of relevance described in the literature in DM include advanced glycated end-product deposition in the myocardium, myofibroblast ‘switching’, autonomic neuropathy, inflammation via TNF-alpha and IL-1b, renin–angiotensin system activation, and blood glucose levels." (PMID 35596784, 2022).
bone metabolic disorders (2 papers, 2013 to 2021). "Activation of renin–angiotensin system (RAS) plays a role in bone deterioration associated with bone metabolic disorders, via increased Angiotensin II (AngII) targeting Angiotensin II type 1 receptor/Angiotensin II type 2 receptor (AT1R/AT2R)." (PMID 34065702, 2021).
bronchopulmonary dysplasia (2 papers, 2015 to 2022). Bronchopulmonary dysplasia is a chronic respiratory disease that results from complications related to lung injury during the treatment of infant acute respiratory distress syndrome in low-birth-weight premature infants or from abnormal lung development in older infants. "Their comorbidities varied and included surfactant dysfunction, bronchopulmonary dysplasia, premature closure of the ductus arteriosus, high levels of renin and aldosterone, and Swyer–James–Macleod syndrome." (PMID 35884048, 2022).
C3 glomerulopathy (2 papers, 2025). "Thus, renin/C3 correlations would be skewed due to pharmacological intervention thereby increasing renin, and the presence of nephritic factors or genetic variants in C3 glomerulopathy, which would lower C3 levels." (PMID 40242769, 2025). "Likewise, patients with complement-mediated kidney disease, such as C3 glomerulopathy, are often treated with angiotensin-converting enzyme (ACE) inhibitors or angiotensin receptor blockers, which markedly increase renin levels." (PMID 40242769, 2025).
cardiac interstitial fibrosis (2 papers, 2015 to 2024). "The pathogenesis of perivascular and interstitial cardiac fibrosis involves the response to hormonal stimuli, primarily related to the renin-angiotensin-aldosterone system and hemodynamic stimulation, specifically increased blood pressure and inflammatory mechanisms." (PMID 38836809, 2024).
cardiopulmonary diseases (2 papers, 2016 to 2021). "Studies investigating the impacts of several cardiopulmonary diseases and renin–angiotensin system modulators on angiotensin-converting enzyme 2 expression and activity." (PMID 34745001, 2021). "Actually, renin–angiotensin system has been recognized to play an important role in developing cor pulmonale." (PMID 26998756, 2016).
coronary vasospasm (2 papers, 2014 to 2025). Sudden coronary artery smooth muscle contraction leading to lumen constriction and decreased blood flow. "Other pathophysiological mechanisms of coronary vasospasm in pregnancy may be due to increased renin release and angiotensin production from uterine hypoperfusion." (PMID 25105029, 2014).
dense deposit disease (2 papers, 2019 to 2022). "Administration of a renin inhibitor in three patients with dense deposit disease (DDD), a rare kidney disease characterized by complement hyperactivation, decreased plasma C3a and C5a levels and complement deposition in the renal biopsy." (PMID 31428128, 2019).
Dent disease (2 papers, 2017 to 2020). Dent disease is a rare genetic renal tubular disease characterized by manifestations of proximal tubule dysfunction. "Remarkably, renin and angiotensinogen massively rise (up to 40-fold) in urine of patients with Dent’s disease or Lowe syndrome, and the same occurs in urine of megalin knockdown mice [15•], or after megalin inhibition with lysine." (PMID 32172431, 2020). "This is evidenced by the up to 40-fold higher urinary renin levels in patients with Dent’s disease or Lowe syndrome, in whom tubular reabsorption of filtered renin (by megalin) is disturbed." (PMID 28118402, 2017). "Furthermore, megalin determines the level of RAS components in urine, and in the absence of megalin (like in Dent’s disease or Lowe syndrome), urinary renin and angiotensinogen levels can easily rise by 2 orders of magnitude." (PMID 32172431, 2020).
End Stage Liver Disease (2 papers, 2022 to 2023). Final stage of a liver disease when the liver failure is irreversible and LIVER TRANSPLANTATION is needed. "Increased baseline model for end-stage liver disease score, white cell count, calprotectin, CD163, tumor necrosis factor, renin, atrial natriuretic peptide, and syndecan-1 were associated with 3-month mortality." (PMID 35333783, 2022).
familial juvenile hyperuricemic nephropathy (2 papers, 2015 to 2024). "Mutations in this gene can lead to different tubulointerstitial nephropathies, including MCKD2, glomerulocystic kidney disease, and familial juvenile hyperuricemic nephropathy, which may also be caused by mutations in TCF2 (HNF1ß) and REN (renin)." (PMID 24584572, 2015).
Fanconi anemia (2 papers, 2021 to 2023). Fanconi anemia (FA) is a hereditary DNA repair disorder characterized by progressive pancytopenia with bone marrow failure, variable congenital malformations and predisposition to develop hematological or solid tumors. "KEGG cluster analysis showed that the renin–angiotensin system, Fanconi anemia pathway, SLE, ECM–receptor interaction, neutrophil extracellular trap formation, and peroxisome proliferator activated receptor signaling pathway were significantly enriched." (PMID 38013304, 2023). "Among these, a total of 23 pathways were involved in the 12.5 μg/ml WSPM10 group, and the enrichment pathways were arranged according to their significance from high to low (P < 0.05), as follows: the renin-angiotensin system, the fanconi anemia pathway, and the steroid biosynlife pathway." (PMID 34340691, 2021).
fibromuscular dysplasia (2 papers, 2016 to 2024). A disorder characterized by fibrous thickening of the arterial wall resulting in narrowing of the arterial lumen. "A diagnosis of fibromuscular dysplasia (FMD) is reasonable given the changes in renin and angiotensin levels, the presence of main renal artery occlusion, the absence of immunological markers, the absence of renal artery calcification, and the lack of a specific family history." (PMID 39439670, 2024).
hemorrhage (2 papers, 2014 to 2022). Loss of blood from the vascular compartment to the exterior or into nonvascular body space as a result of rupture or severance of the blood vessels. "Vasopressin and the renin-angiotensin system are important after hemorrhage as they affect blood pressure and volume; however, they may also influence hemostatic competence." (PMID 25546432, 2014).
hypoadiponectinemia (2 papers, 2012 to 2022). "In this review, we include a rationale for that process, including a discussion about possible putative factors (such as increased renin–angiotensin–aldosterone activity, sympathetic overdrive, hemodynamic alterations, hypoadiponectinemia, hyperleptinemia, and concomitant heart diseases)." (PMID 35457013, 2022).
idiopathic pulmonary arterial hypertension (2 papers, 2021 to 2022). A sporadic form of pulmonary arterial hypertension (PAH) characterized by elevated pulmonary arterial resistance leading to right heart failure. "A study analyzed blood specimens from 79 patients with idiopathic pulmonary arterial hypertension (IPAH) and showed significantly elevated levels of renin, angiotensin I, and angiotensin II, further suggesting a role for RAAS activation in PH." (PMID 34957267, 2021).
Infertility (2 papers, 2022 to 2025). "Another mechanism that might explain the infertility-CVD connection involves over-activation of the renin–angiotensin–aldosterone system (RAAS) during certain infertility treatments." (PMID 41378097, 2025).
Kidney Cyst (2 papers, 2015 to 2025). Abnormal fluid filled sac within the kidney, either acquired or congenital. "For example, it has been shown that kidney cyst and cystic fluid contains renin, angiotensin II (AngII), and angiotensinogen (Agt)." (PMID 25999403, 2015). "Beyond hepatic effects, physiological changes during pregnancy, such as the activation of the renin–angiotensin–aldosterone system, elevated circulating vasopressin and increased renal blood flow, may also contribute to accelerated kidney cyst formation and growth and TKV growth." (PMID 40507450, 2025).
lung adenocarcinoma (2 papers, 2017 to 2020). A carcinoma that arises from the lung and is characterized by the presence of malignant glandular epithelial cells. "The study assessed the existence and significance of associations between the expression of fifteen renin-angiotensin system component genes and lung adenocarcinoma." (PMID 28791183, 2017).
metastatic malignant melanoma (2 papers, 2020 to 2025). "Despite these findings, investigation into the use of renin–angiotensin system inhibitors in the treatment of metastatic melanoma in humans remains limited." (PMID 39941158, 2025). "We have identified components of the renin–angiotensin system in metastatic melanoma to the head and neck lymph nodes and the brain." (PMID 39941158, 2025). "This is relevant, as metastatic melanoma express components of the renin–angiotensin system: PRR, AT2R, and ACE, with ACE localizing to the endothelium of tumor microvessels." (PMID 39941158, 2025). "The expression of components of the renin–angiotensin system by phenotypic CSCs in metastatic melanoma, coupled with the interactions between the renin–angiotensin system and the overactive Ras/RAF/MAPK/ERK and PI3K/AKT/mTOR pathways, present vast therapeutic possibilities." (PMID 39941158, 2025). "However, there are limited studies investigating the renin–angiotensin system in other specific metastatic melanoma subsites." (PMID 39941158, 2025).
Mitral regurgitation (2 papers, 2018 to 2023). An abnormality of the mitral valve characterized by insufficiency or incompetence of the mitral valve resulting in retrograde leaking of blood through the mitral valve upon ventricular contraction. "Fluid overload and increased ventricular volumes, therefore, foster left ventricular remodeling and mitral regurgitation both directly, through myocardial stretch and indirectly, through the activation of the renin-angiotensin-aldosterone, adrenergic, and cytokine systems." (PMID 29805771, 2018).
morbid obesity (2 papers, 2020 to 2023). An excess of body weight, normally defined as an individual with a body mass index greater than 35 or a body weight greater than one hundred percent of ideal body weight. "Moreover, patients with morbid obesity have higher plasma concentrations of renin, angiotensinogen, ACE, Ang II, and aldosterone, activating the renin–angiotensin–aldosterone system (RAAS)." (PMID 32806722, 2020).
Multiple Myeloma (2 papers, 2014 to 2019). "RENIN, ANGTS, and ACE I mRNA expression levels of CBM were significantly higher than those in myeloma patients (p=0.03, p=0.002, and p=0.0008, respectively)." (PMID 25035670, 2014). "In this study, CD34+MM hematopoietic cells also locally expressed RENIN, ANGTS, and ACE I mRNA, indicating the activity of RAS in myeloma-related progenitor cells." (PMID 25035670, 2014). "In the present study, RENIN and ANGTS mRNA expressions were significantly higher in CD34+ hematopoietic stem cells of healthy allogeneic donors in comparison to myeloma-related progenitor cells." (PMID 25035670, 2014). "Likewise, RENIN, ANGTS, and ACE I mRNA expression levels of CBM were significantly higher than those in the myeloma patients." (PMID 25035670, 2014). "Moreover, RENIN and ANGTS mRNA expression levels were significantly higher in CD34+ stem cell samples of healthy allogeneic donors compared to those in myeloma patients (p=0.001 and p=0.01)." (PMID 25035670, 2014).
Multiple Organ Failure (2 papers, 2020 to 2023). A progressive condition usually characterized by combined failure of several organs such as the lungs, liver, kidney, along with some clotting mechanisms, usually postinjury or postoperative. "Research has revealed the relationship between multiple organ failure and pyroptosis in SARS-CoV-2 infection, where the binding of ACE2 to the spike protein overactivates NLRP3, leading to the activation of the renin–angiotensin–aldosterone system and complement cascade." (PMID 38002346, 2023).
nasal polyp (2 papers, 2026). "Enrichment analysis of nasal polyp tissues revealed that the most significantly upregulated gene sets were involved in positive regulation of extracellular signal-regulated kinase 1/2 cascade, hypoxia-inducible factor-1 pathway, overactivation of renin-angiotensin-aldosterone system and ferroptosis." (PMID 41948328, 2026).
nonalcoholic steatohepatitis (2 papers, 2013 to 2022). "Activation of the renin-angiotensin-system is known to play a role in nonalcoholic steatohepatitis." (PMID 24204981, 2013).